TNF (tumor necrosis factor)
Diseases named in the same sentence as TNF in open-access papers (continued):
Sharing a sentence is not in itself a finding about the gene and the disease.
infection (continued). "In the infection site, T. cruzi triggers the production of chemokines and pro-inflammatory cytokines, such as interleukin-12 (IL-12) and tumor necrosis factor-a (TNF-α), and the highly reactive oxygen and nitrogen species produced by cells of the Mφ lineage." (PMID 30787935, 2019). "At the transcriptional level, the TNF gene is induced in response to a diversity of specific stimuli including inflammation, infection, and stress." (PMID 31816903, 2019). "Noteworthy, A/J C5−/− mice have higher levels of TNF-α, IL-6, and IL-10 in the kidney when compared to A/J C5+/+ mice on the third day of infection." (PMID 31687410, 2019). "During follow-up, a total of 29 infections were registered, 89.66% (n = 26) in the anti-IL-6R group and 10.34% (n = 3) in the anti-TNFα group." (PMID 31261772, 2019). "Samples of paw tissue were collected at day 40 after the infection to evaluate TNF-α and IL-1β production, MPO activity levels, and histopathological analysis." (PMID 31138231, 2019). "Upon infection, pro-inflammatory cytokines such as TNFα, IL-1β, IL-6, IL-8 are secreted in the CSF and pneumococci and leukocytes infiltrate the perilymphatic space of the inner ear via the cochlear aqueduct." (PMID 31244750, 2019). "The relative expressions of IL-1β, IFN-α, TNF-α, and NF-κB over the course of the infection were detected by qPCR method." (PMID 30760749, 2019). "As expected, a strong proinflammatory response, demonstrated by drastic cytokine expression, including IL-6 and TNF-α, was observed early upon infection." (PMID 31998663, 2019). "Like natural infection, a gradual surge in the levels of IL-4, IL-10, and TGF-β were observed, while the levels of IFN-γ and TNF-α increased gradually at early infection but were reduced to basal level at chronic infection." (PMID 31031744, 2019). "The results showed that infection of macrophages with the ∆stir-2 mutant increased the expression of IL-6, IL-1β, and TNF-α at 18, 24, and 48 hpi compared with macrophages infected with the wild-type SC09 strain or the ∆stir-2 + pSTIR-2 mutant strain." (PMID 31500298, 2019). "As innate TNF-α dependant mechanisms drive cell mediated immunity by activation of CD4+ and CD8+ T cells, TNF-α is known to be fundamental in the initial control of the infection together with other cytokines such as IL-12 and IFN-γ." (PMID 31469834, 2019). "Immediately after infection, inflammatory responses are elicited; for instance, the number of somatic cells and levels of inflammatory cytokines, such as tumor necrosis factor (TNF)-α, interleukin (IL)-6, and IL-8, increase in milk." (PMID 31019541, 2019). "Blood TNF-α and IL-1β levels and systemic parasite burden were evaluated 5–40 days after the infection." (PMID 31138231, 2019). "Other studies investigating the role of anti-TNF-α in granuloma formation/maintenance showed that TNF-α blockers also impact the response to infection by interfering with phagosome maturation and/or by modulating apoptosis and cell death of immune cells." (PMID 31475008, 2019). "In acute inflammation and infection, leptin levels increase due to the presence of bacterial endotoxins and other signaling cytokines like TNF-a, IL-6, and IL-1b." (PMID 31186010, 2019). "The chemokines CCL5, CCL9, CXCL10, and CCL2 attract immunity cells at the site of infection and their production is stimulated by TNF-α and boosts the production of NO by MΦ." (PMID 31508399, 2019). "TNFα is a proinflammatory cytokine produced in response to the foreign invasion, and is often the main cytokine produced by macrophages following infection." (PMID 30813415, 2019). "A higher incidence of serious infections has been seen in elderly patients with RA treated with anti-TNF agents (infliximab, adalimumab, etanercept) and Janus kinase inhibitors (tofacitinib or baracitnib)." (PMID 31429794, 2019). "Release of cytokines, for example, IL-1β and TNF-α, can activate and recruit effector inflammatory cells to the site of infection." (PMID 31998291, 2019).
infection (continued). "Both C38901 infection and IL-17C stimulation upregulated IL-8 and TNF-α transcripts in IPEC-J2 cells as compared to control or HB101 treated cells." (PMID 31221216, 2019). "Susceptible sheep, on the other hand, usually present higher mRNA levels of TNFα and IL1β in the gut mucosa and respective lymph nodes, at the early and late infection." (PMID 31815153, 2019). "Strikingly, we observed that three major inflammatory cytokines (IL-6, TNF-α, and IL-1β) were produced less during infection in AIC than in LCC." (PMID 31801841, 2019). "At 12 h after the infection, interferon-gamma, interleukin-10, interleukin-17A, interleukin-1 beta, interleukin-6, and tumor necrosis factor alpha (TNF-α) tended to be suppressed with micafungin treatment in both PF and control mouse models." (PMID 31249356, 2019). "MDMs infected at a Map multiplicity of 1:4 display transcription-level shifts in cytokine expression marked by upregulation of TNF-α by 15-fold by day 5 post-infection with concurrent downregulation of IL-10." (PMID 31614819, 2019). "Modest increases in IFN-γ during infection with Y. pestis have previously been reported along with the late arrival of TNFα, also demonstrated here." (PMID 31546628, 2019). "After infection with E. coli, markedly reduced serum TNF‐α and IL‐12p70 levels were observed in HDAC2 knockdown BMM‐transferred mice compared with their control littermates." (PMID 30207412, 2019). "We observed that huNSG mice that were infected with 105 infectious EBV particles also had significantly higher serum levels of IFNγ, TNFα, IL-10, and IL-2 compared to infection with 103 infectious EBV particles or PBS treated huNSG animals." (PMID 31145756, 2019). "Compared to CD8+CXCR5- T cells, CD8+CXCR5+ T cells produce different levels of interferon (IFN)-γ and tumor necrosis factor (TNF)-α during infection with lymphocytic choriomeningitis virus (LCMV) or HIV, and in chronic infections." (PMID 31663864, 2019). "Both infection groups showed a continuous decrease of pro-inflammatory cytokine concentrations, including TNF-α, IFN-γ, GM-CSF and IL-6, in the cerebrum over the course of infection." (PMID 31315623, 2019). "For example, F. tularensis strain LVS induces the production at substantial levels of TNF-α within 60 min after infection of various human as well as murine monocyte/macrophage cells." (PMID 31334134, 2019). "The results showed that the lung tissues of LL37+/+ mice released less TNF-α and IL-6 than did those of wild-type mice after 2 days of infection." (PMID 30842778, 2019). "Such cytokines as IFNβ or TNFα that are produced immediately after infection or after activation of mononuclear phagocytic cells by microbial components can affect the microenvironment of those cells that will be infected in the following order." (PMID 31334134, 2019). "Protein levels of the pro-inflammatory cytokines IL-8 and TNF-α were also investigated in the supernatant of control and infected cultures at different time-points post-infection." (PMID 31068227, 2019). "It has been shown that TNFα is crucial for the macrophage activation and recruitment with subsequent formation of granulomas in order to limit the infection of Mycobacterium tuberculosis." (PMID 31739600, 2019). "These proteases affect also the integrity of the cytokines IL-6, IL-8, IL-12, and TNF-α, which are produced in response to the infection." (PMID 31049022, 2019). "Innate immunity is a rather unspecific and immediate reaction that recruits immune cells to the injury or infection site through various cytokines (e.g., prostaglandins, tumor necrosis factor (TNF), interleukin (IL)-1β, and others)." (PMID 31295952, 2019). "TNF‐α was also significantly elevated in the chinchilla middle ear after pneumococcus inoculation but at a later time point (72 hrs) following infection." (PMID 30265765, 2019).
infection (continued). "Further, IOE infection induced statistically higher percentage levels of iNOS+(near 2-fold) and TNF-α+ cells (near 2-fold), when compared to uninfected controls." (PMID 31575880, 2019). "Leukocyte migration during conditions of tissue injury or infection is a multi-step process involving local upregulation of proinflammatory chemokine secretion in response to signaling molecules such as TNF-α and IFN-γ." (PMID 30894217, 2019). "Second, the early internalization of Brucella-infected PMNs by Mφs, seems to occur in a non-phlogistic manner, displaying significant amounts of regulatory IL-10 and low quantities of proinflammatory cytokines, such as TNF-α at early stages of the infection." (PMID 31134082, 2019). "Following transcription and translation, cytokines such as interleukin 1 (IL-1) and TNFα are secreted from cells to coordinate both, locally and systemically the inflammatory host cell response to tissue damage and infection." (PMID 31242600, 2019). "They suggest a functional model, where infection with E. coli activates TNF and consecutive TACE secretion in PBMO." (PMID 30897723, 2019). "Infection of hPCLS resulted in increased levels of tumor necrosis factor alpha (TNF-α), interleukin-6 (IL-6), and IL-8 in response to the Δpla strain compared to those in response to wild-type Y. pestis at 2 hpi." (PMID 31085709, 2019). "Rebounders also exhibited a higher cell infection efficacies, despite an early predominance of antiviral cytokines (IFNγ, IFNα, TNFα) over immuno-modulatory cytokines (IL10, TGFβ)." (PMID 30696429, 2019). "Of note, we found significantly elevated levels of IL12p70, INFγ, and TNFα in the sera of infected WT/Ami mice on day 10 post infection compared to infected WT mice." (PMID 31275322, 2019). "This has confirmed that MCs are responsible for the synthesis and release of de novo mediators such as TNF-α in a prolonged period of infection by DENV." (PMID 31110077, 2019). "panamensis infected C57BL/6 mice, which are unable to activate TLR-dependent pathways, have a decreased ability to secrete TNF and an increased parasite burden early in the infection." (PMID 31119102, 2019). "Contrary to murine VL, the role of IL-6 in human VL is associated with disease severity and death, which is due to the inhibition of TNF-α in the early phase of infection and later by inhibiting the Th1 responses." (PMID 31024534, 2019). "Infection and local tissue injury generate the release of proinflammatory cytokines including TNF-α and IL-6, which contribute to increased systemic inflammatory responses." (PMID 31885498, 2019). "Similar observations have been reported in animal model for IFN-γ and TNF-α between co- and mono-infection of trypanosome and plasmodium." (PMID 31687034, 2019). "In the liver, the three reference genes were validated against TNF-α and IL-1β during chronic stages of infection with F. hepatica and in uninfected controls." (PMID 30728395, 2019). "The TNF-α plays a key role in parasite control and infection pathology in T. brucei infections, similar to IFN-γ." (PMID 31687034, 2019). "Although both invasive isolates induced high levels of TNF-α production, the fold change from mock infection was three to six-fold lower than what was observed for the other three strains recovered from colonized mothers." (PMID 31536604, 2019). "The infection of mast cells with Chlamydia elicits the secretion of cytokines such as TNF-α and IL-4, which promotes the infiltration of immune cells into the airways by opening tight junctions, thereby improving chlamydial propagation." (PMID 31333596, 2019). "In response to injury, TNF-α functions to restore brain homeostasis during acute inflammation, acting as a defensive guard to protect against CNS injury, infection, neurodegeneration, and neurotoxicity." (PMID 31867326, 2019). "S. Typhimurium induced the expression of IL-6, IL-8, IL-1β, TNFα and IL-10 genes in CaCo-2 cells after 8-h infection." (PMID 31490973, 2019).
infection (continued). "The number of patients with observed infection in TNF-alpha inhibitor groups and control groups was used to calculate the odds ratio (OR)." (PMID 30658717, 2019). "Initially, in vitro studies as well as data derived from zebrafish infection models suggested that tumor necrosis factor alpha (TNFα) and mixed lineage kinase domain-like- (MLKL) driven necroptosis is the main cell-death pathway exploited by Mtb10,11." (PMID 30737374, 2019). "In keeping with previous findings, direct TNF-α production by yeast strain modulated Th1/Th2 balance during infection, and drove the improved co-stimulatory activation of CD103+ cDC1, reported to be specialized in promoting Th1 response." (PMID 31404168, 2019). "Proinflammatory cytokines including IL-1β, IL-6, IL-8, and TNF-α are upregulated and peak at 48 hpi in primary PAMs during infection." (PMID 31363150, 2019). "Our studies found that the transgenic strain with TNF-α production enhances fungal containment by the host at the very early innate phase of infection." (PMID 31404168, 2019). "Macrophages are the principal cells that acquire E. coli at early time points post infection and start to produce TNF-α, KC and MIP-2 in order to coordinating the exact recruitment and response of granulocytes in the infected urothelium." (PMID 30643171, 2019). "To assess this, we injected larvae with TNF 1-day post infection (dpi) to create TNF-high animals (see STAR Methods)." (PMID 31474371, 2019). "Following infection, cytokines, such as IL-1β, IL-6, TNF-α, and inducible nitric oxide synthetase (i-NOS), that coordinate immune/inflammatory responses are triggered and activated." (PMID 30814582, 2019). "This TNF plays role in systemic inflammation and is a cytokine involved during acute phase infection by regulating the immune cells." (PMID 31847806, 2019). "We further investigated soluble proinflammatory cytokines in plasma and lung homogenates (IL-1β, KC/GRO, TNFα, IL-6, IL-12p70, and IFNγ) as well as pulmonary influx of myeloid-derived cells 2 weeks into COXi treatment (week 6 of infection)." (PMID 31396568, 2019). "This process ensues the development of a cytokine cascade, some of them with protective roles, including IL-12, IL-13, IL-6, CXLL2, CCL7, CCL2, TNF-α, and consequent neutrophils recall in the site of infection." (PMID 31508399, 2019). "The aim of this meta-analysis was to investigate the observed infections in JIA children during tumor necrosis factor (TNF)-alpha inhibitor therapy." (PMID 30658717, 2019). "α1,3GalT-WT mice showed high levels of IFN-γ, TNF-α, and IL-10 in the early stage of infection (day 7)." (PMID 30911415, 2019). "For example, while the production of IFN-γ and TNF-α are critical for protection during infection with African trypanosomes, their production in excessive amounts is detrimental and leads to susceptibility and death of infected mice." (PMID 31824512, 2019). "The infection of the ileal loop with S. dysenteriae increased both the protein and mRNA expression levels of proinflammatory cytokines IL-8 and TNFα." (PMID 31611869, 2019). "Our current treatment module with SSD–CSM-FPEG resulted in a decrease of pro-inflammatory cytokine TNF-α and increase in anti-inflammatory cytokine IL-10, indicating a resolution of inflammation following subsidence of infection." (PMID 31194776, 2019). "The cell culture supernatants were subjected to sandwich ELISA for the detection of TNF at early (6 hpi) and late (12 hpi) time post-infection." (PMID 31031770, 2019). "Whereas TNFα secretion was increased upon infection independently of pilus expression, pilus-positive gonococci caused an increase in IL-8 and suppression of IL-6 secretion." (PMID 31417529, 2019). "IL-6 is considered one of the most important cytokines during an infection, along with interleukin 1 (IL-1) and tumor necrosis factor alpha (TNF-a; Dienz and Rincon, 2009)." (PMID 31134045, 2019).
infection (continued). "After infection or stimulation, RNA samples were harvested and analysed for the expression of IFNβ mRNA, as well as TNFα mRNA as a control using RT-qPCR." (PMID 30634661, 2019). "Astrocytes respond to infection by synthesizing pro-inflammatory and anti-inflammatory cytokines, such as interleukin-1β and tumor necrosis factor-α (TNF-α)." (PMID 31231189, 2019). "Infection of murine bone marrow-derived macrophages (BMDMs) with TIGR4 strains demonstrated that macrophage TNF and IL-6 responses to S. pneumoniae were, as expected, highly dependent on TLR2." (PMID 31551336, 2019). "Neonates are deficient in the production of the pro-inflammatory cytokine TNF-α and its receptors, TNF-α receptor I and II, increasing susceptibility to infection due to immune cell dysregulation." (PMID 31861718, 2019). "Our data demonstrate that mice infected with the ΔmsbA strain showed a reduction of important inflammatory mediators like TNF-α and IL-1β, resulting in almost a 30% reduction of both cytokines, after 24 h of infection." (PMID 31217305, 2019). "Compared with blank group, the pro-inflammatory cytokine IL-1β and TNF-α expression levels from other groups were similar, the results demonstrate that the infection of APEC changed from acute period to prognosis." (PMID 31513649, 2019). "We especially focused on TNF-α and VDR genes because the elderly are often associated with hospitalization, severe infection, and disability." (PMID 31887189, 2019). "As a further infection control mechanism DCs favor the development of T lymphocytes with γδ receptor through TNF-α and IL-12 production." (PMID 31508399, 2019). "First, we showed that after infection with L. braziliensis there is an increase in TNF expression and it occurs predominantly in TLR2 (+) and TLR4 (+) cells." (PMID 31119102, 2019). "Overall, these findings support that TNF-α expression by H99-α effectively activates the innate defenses to substantially reduce fungal burden right at the onset of the infection." (PMID 31404168, 2019). "CRP is persistently produced during infection in the acute phase response via tumor necrosis factor α (TNF- α), interleukin -1β (IL 1 β) and IL-6." (PMID 31856765, 2019). "It is released later in infections compared to inflammatory cytokines, as tumor necrosis factor (TNF)-α and interleukin (IL)-1β." (PMID 31847111, 2019). "TNF-α plays a key role in the process of controlling infection that ranges from limiting the replication of the parasite up to eliciting an effective adaptative response." (PMID 31469834, 2019). "The NH36 vaccine also enhanced the TNF-α secretion whereas, after infection, the F3 vaccine induced the strongest IFN-γ and TNF-α secretions while the chimera was dominant for production of IL-10." (PMID 31024556, 2019). "Resolved mice were treated with anti-TNFα or isotype control antibody 18 hr prior to infection with 107 cfu UTI89 and sacrificed at indicated time points." (PMID 31429405, 2019). "In response to M. tuberculosis or rIAV, CXCR6KO mice developed Th1 cells, but at the peak of the effector response in both infections, there were reduced numbers of lung Th1 cells secreting IFNγ and TNFα." (PMID 30899256, 2019). "In fish, many studies have indicated that regulation in T cells and B cells were mediated by cytokines such as TNF-α and IL-1β, or infection by pathogens." (PMID 31798571, 2019). "Inflammation or infection of the placenta induces a robust signaling response, including increased concentrations of IL-1β, IL-6, IL-8 and TNF." (PMID 31537532, 2019). "Some studies reported that infection was more frequent soon after the start of treatment with TNF inhibitors, and the same tendency was noted in the present study." (PMID 30611312, 2019). "The dynamic curves of the levels of CRP, IL-6, IL-8, IL-10, SCD163 and TNF-α in both groups demonstrated a similar trend during infection but differences between the groups was observed only in the sTREM-1 levels." (PMID 31387541, 2019).